LINC02086 (long independently transcribed non-coding RNA 2086)
Gene: Long non-coding RNA gene on chromosome 17 (48,642,627 to 48,707,346, forward strand). Ensembl gene ENSG00000244649.
Diseases named in the same sentence as LINC02086 in open-access papers:
LINC02086 is named in the same sentence as 7 diseases in open-access papers, as found by Europe PMC text mining. Sharing a sentence is not in itself a finding about the gene and the disease. The quoted sentences say what the papers report.
breast carcinoma (1 paper, 2023). "Furthermore, sponge miRNAs, downstream target proteins and their biological activities were explored to decode the underlying molecular mechanisms of LINC02086 in breast cancer." (PMID 38008720, 2023). "Our study aims to characterize the functions of LINC02086 which few published in breast cancer and decipher the downstream molecular mechanisms." (PMID 38008720, 2023). "Our study suggested that LINC02086 exhibited oncogenic activities in breast cancer, as evidenced by decreased cell viability, strengthened cell apoptosis and suppressed tumor growth as results from LINC02086 knockdown." (PMID 38008720, 2023). "In conclusion, our study provides in vivo and in vitro evidences that LINC02086 acts as a tumor-promoter, enhancing cell viability and suppressing cell apoptosis in breast cancer through the regulation ofmiR-6757-5p/EPHA2 axis." (PMID 38008720, 2023). "LINC02086 expression was up-regulated in breast cancer tissue using RNA-seq data of GEPIA database." (PMID 38008720, 2023). "This is the first study that reports the pro-tumorigenic role of LINC02086 in breast cancer." (PMID 38008720, 2023). "Our study focused on the uncharacterized LINC02086 in breast cancer." (PMID 38008720, 2023). "LINC02086 expression is tested in RNA-seq data from GEPIA database, tumor tissue samples from hospital patients and breast cancer cell lines." (PMID 38008720, 2023). "Although there are limited articles revealing the function of LINC02086 in breast cancer, our study observed an upregulation of LINC02086 in RNA-seq data from the GEPIA database, tumor tissue samples, and breast cancer cells." (PMID 38008720, 2023). "However, the functional roles and clinical significance of LINC02086 in breast cancer have not been dissected." (PMID 38008720, 2023).
gastric cancer (1 paper, 2024). A primary or metastatic malignant neoplasm involving the stomach. "Finally, we determined that LINC02086 has biological effects that promote the proliferation and migration of gastric cancer cells." (PMID 38370380, 2024). "In addition, for LINC02086, our study also confirmed that its knock down has biological functions including cell cycle arrest, inhibiting cell proliferation and metastasis in gastric cancer cells." (PMID 38370380, 2024). "In the ceRNA network, MMP3 and LINC02086 could competitively bind miR-93-5p, as directly confirmed by our dual luciferase reporter assay in vitro, and in the LINC02086 knock down gastric cancer cells, MMP3 was accordingly down-regulated in both mRNA and protein levels." (PMID 38370380, 2024). "Therefore, to validate our bioinformatics findings, we performed RT-qPCR to determine the expression levels of LINC02086 and LINC02535, which demonstrated a substantial up-regulation of their expression in gastric cancer cells, aligning with our bioinformatics prediction." (PMID 38370380, 2024).
lung adenocarcinoma (1 paper, 2023). A carcinoma that arises from the lung and is characterized by the presence of malignant glandular epithelial cells. "Previously, it reports that LINC02086 is related to glycolysis and immune in lung adenocarcinoma." (PMID 38008720, 2023).
cancer (1 paper, 2023). A tumor composed of atypical neoplastic, often pleomorphic cells that invade other tissues. "In the patients cohort, miR-6757-5p level was decreased in cancer tissue samples compared to normal tissue samples (p-value < 0.001), and was negatively correlated with LINC02086 level (Pearson r = -0.5698, P < 0.001)." (PMID 38008720, 2023). "However, lots of function of LINC02086 in cancers remains unknown." (PMID 38008720, 2023).
LINC02086 also shares sentences with these, for which no sentence is quoted: hepatocellular carcinoma (1 paper); larynx carcinoma (1); tumor (1).